LASP1 (LIM and SH3 protein 1)
Diseases named in the same sentence as LASP1 in open-access papers (continued):
Sharing a sentence is not in itself a finding about the gene and the disease.
Parkinson disease (1 paper, 2022). A progressive degenerative disorder of the central nervous system characterized by loss of dopamine producing neurons in the substantia nigra and the presence of Lewy bodies in the substantia nigra and locus coeruleus. "In the subacute treatment setting, miR-218-5p was significantly upregulated at the end point, which is in agreement with decreased dopaminergic neuron loss in Parkinson’s disease patients due to miR-218-5p targeting LASP1." (PMID 35884935, 2022).
squamous cell lung carcinoma (1 paper, 2017). A carcinoma arising from squamous bronchial epithelial cells. "Furthermore, in patients with squamous cell lung carcinoma, positive Lasp1 expression also indicated adverse clinical outcome (P<0.001)." (PMID 29088849, 2017).
stomach adenocarcinoma (1 paper, 2018). "To explore the signaling downstream of LASP1, we analyzed TCGA dataset of stomach adenocarcinoma and found that the level of AKT phosphorylated at Ser473 was positively correlated with the expression of LASP1 mRNA." (PMID 29980193, 2018).
testis cancer (1 paper, 2024). "Almost all of the top-performing genes were that of over-expression, with PMS2 in THYM; CARD11, LASP1, STIL, POLE, KMT2C, and CLIP1 in testis cancer; ERC1, WRN, OLIG2, FANCC, and ACSL6 in ACC; and SOX2 and NDRG1 in ESCA leading in performance with AUCs ranging 0.832-0.911." (PMID 38491101, 2024).
urinary tract infection (1 paper, 2015). "However, urine contamination with erythrocytes above 250 cells/μl and urinary tract infections yielded false positive results, thus limiting the broad usability of urinary LASP1 levels as TCC-biomarker to cases without urinary tract infection or gross hematuria." (PMID 25622104, 2015).
tumor (97 papers, 2007 to 2025). "LASP1 is frequently overexpressed in various types of cancer, including lung, breast, ovarian, and colorectal cancer, and is associated with increased tumor aggressiveness, metastasis, and poor prognosis." (PMID 40863728, 2025). "Clinically, overexpression of LASP1 is associated with tumor metastasis and poor prognosis of NPC patients." (PMID 29531214, 2018). "The results of the present study were consistent with the previous studies that overexpression of Lasp1 was associated with larger tumor size, advanced TNM staging and positive lymph node metastasis." (PMID 29088849, 2017). "Association analyses revealed that LASP-1 upregulation was significantly associated with larger tumor size and worse TNM stage." (PMID 24955835, 2014). "Similarly, high PUS7 positive staining was significantly linked to T classification, and high LASP1 positive staining was significantly linked to tumour size, T classification, and clinical stage." (PMID 33990203, 2021). "Moreover, a subcutaneous tumor model confirmed that LASP1 was strongly associated with the tumor growth and therapy effect of TMZ." (PMID 29980193, 2018). "Also, MiR-218 was significantly downregulated in PCa clinical specimens and loss of tumor-suppressive miR-218 enhanced cancer cell migration and invasion in PCa through direct regulation of LASP1." (PMID 28030804, 2017). "Overexpression of LASP1 is associated with increased tumor aggressiveness of numerous cancers, suggesting that LASP1 protein levels may serve as a prognostic marker." (PMID 25622104, 2015). "In conclusion, our data indicated that LASP-1 may be associated with tumor progression by promoting cell-cycle progression in the G2 phase." (PMID 24386158, 2013). "Therefore, further exploring the functional regulation of LASP-1 and its interacting proteins by Ubiquitin C-associated ubiquitination pathway in different tumours will help us better understand the molecular mechanism of carcinogenesis associated with LASP-1 and its interactors." (PMID 28266596, 2017). "In DLBCL, expression of miR-665 can suppress tumor progression by targeting and inhibiting LIM and SH3 domain protein 1 (LASP1) and MYC, both essential for invasion, migration, and cell proliferation." (PMID 40255571, 2025). "RT-qPCR analyses in the tumor tissues revealed similar expression patterns of circTIAM1, miR-338-3p and LASP1 in the in vitro cell model following silencing of circTIAM1 expression." (PMID 39449799, 2024). "In the 3D spheroid culture, inhibition of miR-338-3p expression and LASP1 overexpression sustained the tumor spheroid formation following knockdown of circTIAM1 expression." (PMID 39449799, 2024). "We observed significant delays to tumour growth in LASP1 KD cells, which resulted in a significant increase in survival, thus providing validation for our in vitro studies." (PMID 38789663, 2024). "This demonstrated that LASP1 KD tumours took an additional 18 days on average to reach an equivalent size." (PMID 38789663, 2024). "Further, animals bearing LASP1 KD tumours displayed significantly prolonged survival (Neg shRNA—median survival of 37 days, LASP1 KD – median survival of 72 days)." (PMID 38789663, 2024). "We further demonstrated that LASP1 expression is also critical for tumour growth in vivo by performing tumourigenicity assays." (PMID 38789663, 2024). "The participation of LASP1 in tumor development has been investigated in several biological models where its useful function as a mediator in pathways leads to tumor growth." (PMID 38204280, 2024). "Given their hyperactivation-promoting tumor abilities, the hsa-miR-1225-5p interaction targets LASP1, PEG10, and MYC that were chosen from curated open data have been thoroughly examined in tumor models with meaningful participation." (PMID 38204280, 2024). "To determine if the tumour suppressive effect of miR-203 is due to the repression of LASP1, we restored LASP1 expression in HeLa and SiHa cells expressing a miR-203 mimic." (PMID 38789663, 2024).
tumor (continued). "Recently, LASP1 was reported to be highly expressed in different tumor tissues to promote cell proliferation and migration by activation of the PI3K/AKT pathway." (PMID 39449799, 2024). "Phosphorylation of LASP1 by uncontrolled activation of PKA/cAMP signaling in tumor cells reduces LASP1 affinity to F-actin." (PMID 36497077, 2022). "This review will focus on specific phosphorylation-dependent interaction between LASP1 and cellular proteins that orchestrate primary tumor progression and metastasis." (PMID 36497077, 2022). "The protein expression level of LASP1 was found to be upregulated in several tumor types, except melanoma." (PMID 36497077, 2022). "LASP1 is a well-known protein that interacts with many proteins regulating tumor cell migration and invasion." (PMID 35027621, 2022). "Analysis of human CCA tissue samples revealed that LASP-1 was markedly overexpressed in tumor compared to healthy tissue." (PMID 35205774, 2022). "LASP1 can increase tumor cell migration and invasion by promoting epithelial-mesenchymal transition." (PMID 35379225, 2022). "Further, several studies have shown that LASP1 plays an important role in tumour development and metastases, and RNAi knock-down of LASP1 has led to strong inhibition of proliferation and migration in various cancer cells." (PMID 36672776, 2022). "LASP1 (LIM and SH3 domain protein 1) was recently identified as a regulator of tumor progression and drug resistance in several cancers, including CCA 25-28." (PMID 34975317, 2022). "An earlier review by the authors summarizes some of the miRNAs that lead to upregulation of LASP1 in specific tumor types." (PMID 36497077, 2022). "It has been recently discovered that LASP1 can trigger the epithelial mesenchymal transition process and promote tumor progression by the PI3K/AKT pathway." (PMID 36091823, 2022). "Previous studies on different cancer cells, including CRC, have been pivotal for the elucidation of the contribution of LASP1 to tumour metastasis." (PMID 33990203, 2021). "In short, the depletion of PPP1R14B-AS1 decreased LASP1 levels via the sequestration of miR-134-3p, consequently impairing tumor growth in vivo." (PMID 37303940, 2021). "LASP1 was widely reported as a potent tumor driver in CRC via activating two survival and proliferation pathways." (PMID 34124372, 2021). "Our studies add further evidence that circBCL11B function as a tumor-promoting factor by targeting miR-579/LASP1 axis in OSCC cells." (PMID 34288804, 2021). "In this study, we first found that LASP1 is related to the metabolism of phospholipids, especially ceramides, in tumor cells, and regulates the lipid-metabolism enzyme ECHS1." (PMID 34615856, 2021). "LIM and SH3 domain protein 1 (LASP1), highly expressed in a variety of tumors, is considered as a novel tumor metastasis biomarker." (PMID 34912481, 2021). "LIM and SH3 protein 1 (LASP1) is a specific focal adhesion protein that promotes metastasis in a variety of tumours." (PMID 31793711, 2020). "The levels of primary tumour LASP1 were clearly increased compared with those of the adjacent normal tissues, according to the real‐time PCR assay." (PMID 31793711, 2020). "From our experiments, LASP1 had a higher expression levels in tumor samples, which was consistent with previous publications." (PMID 32938459, 2020). "Studies have demonstrated that LASP-1 was notably upregulated and promoted tumor proliferation, invasion and metastasis in multiple malignant tumors, including NSCLC." (PMID 32938459, 2020). "This suggests that LASP1 inhibits Let-7a’s tumor suppressor function in response to CXCR4 activity in order to allow for induction of proteins that are involved in the process of cell motility and invasion." (PMID 32872485, 2020). "Although LASP1 was originally identified as a structural cytoskeletal and adaptor protein, an overexpression of LASP1 has been reported in numerous tumor entities and recent data have also provided evidence for its transcriptional activity." (PMID 32075106, 2020).
tumor (continued). "LASP-1 was reported to be regulated by miR-203 and facilitate tumor proliferation and aggressiveness in human NSCLC." (PMID 32938459, 2020). "Next, we noticed that miR-342-3p, a tumor suppressor microRNA, was predicted to interact with LASP1." (PMID 32938459, 2020). "The results prompted us to propose two connected models, explaining the variations in tumor progression in solid breast cancer and hematopoietic malignancy based on differences in LASP1 phosphorylation." (PMID 32075106, 2020). "In this present study, we found that HSPA1A directly binds with LASP1, co‐located in the cell cytoplasm and plays a synergistic role in promoting tumours in HNSCC by elevating the interaction between LASP1 and P‐AKT." (PMID 31793711, 2020). "In human tumor tissues, LASP1 is significantly overexpressed and plays a pivotal role for cancer aggressiveness." (PMID 31372094, 2019). "This brings out the key role played by CXCR4 in enabling the recruitment of eIF4G and LASP1 to enable the synthesis of oncogenic proteins involved in tumor progression and metastasis." (PMID 31106142, 2019). "Further, it functioned as a tumor promoter by promoting cell growth and invasion and repressing cell apoptosis via sponging miR-1294 to repress LASP1." (PMID 30988074, 2019). "Our further analysis found that LASP1 involved in hsa_circ_0004370/miR-1294 pathway as a tumor activator through promoting cell proliferation and invasion and inhibiting apoptosis." (PMID 30988074, 2019). "We further demonstrated that ANLN knockdown significantly inhibited the levels of EZH2 and LASP1 expression in xenograft tumor models." (PMID 31395079, 2019). "In the recent two decades, LIM and SH3 protein 1 (LASP1) has been developed from a simple actin-binding structural protein to a tumor biomarker and subsequently to a complex, nuclear transcriptional regulator." (PMID 30298118, 2018). "In vivo, a subcutaneous tumor model was used to assess the effect of LASP1 on tumor growth and chemosensitivity of TMZ." (PMID 29980193, 2018). "In two independent GBM databases, LASP1 was upregulated in tumor samples compared to in normal tissues (P < 0.001)." (PMID 29980193, 2018). "The effect of LASP1 on GBM proliferation was examined by MTT assay and colony formation assay, the effect of LASP1 on sensitivity of Temozolomide was measured by flow cytometry and subcutaneous tumor model." (PMID 29980193, 2018). "Silencing LASP1 potentiated cell chemosensitivity to temozolomide in vitro, LASP1 knockdown inhibited tumor growth and enhanced the therapeutic effect of temozolomide in vivo." (PMID 29980193, 2018). "Since the discovery of LASP1 in 1995, the protein was observed to be overexpressed in a variety of tumor types and the list is still increasing." (PMID 30298118, 2018). "Hypoxia response elements were identified in the LASP1 promoter and were shown to stimulate LASP1 expression in pancreatic cells in vitro and in mouse tumor xenografts." (PMID 30298118, 2018). "In this respect, LASP1 plays a pivotal role in tumor invasion and metastasis by releasing MMPs into the ECM via specialized cell membrane domains called invadopodia akin to podosomes in normal cells." (PMID 30298118, 2018). "We also investigated the effects of Lasp1 on tumor proliferation and invasiveness after transfected with Lasp1 plasmid or Lasp1-siRNA." (PMID 29088849, 2017). "Tumor proliferation and invasion mediated by Lasp1 overexpression was also reversed by FAK inhibitor incorporation." (PMID 29088849, 2017). "In the present study, using immunohistochemistry, we found that Lasp1 expression was significantly correlated with tumor size (P=0.005), advanced TNM stage (P=0.042), positive regional lymph node metastasis (P=0.034) and poor overall survival (P<0.001)." (PMID 29088849, 2017). "In conclusion, Lasp1 facilitated tumor proliferation and invasion of NSCLC through directly binding to FAK and enhancing the phosphorylation of FAK (Tyr397) and AKT (Ser473)." (PMID 29088849, 2017).
tumor (continued). "In conclusion, the present study indicated that overexpression of Lasp1 correlated with larger tumor size, advanced TNM stage, positive regional lymph node metastasis and predicted poor prognosis of NSCLC patients." (PMID 29088849, 2017). "Results of wound healing test and transwell assay suggested that tumor migration and invasion were enhanced after transfecting Lasp1 plasmid in A549 cells, but were depressed after transfecting Lasp1 siRNA in H460 cells." (PMID 29088849, 2017). "Statistical analysis results showed that positive expression of Lasp1 was significantly correlated with larger tumor size (P=0.005), advanced TNM stage (P=0.042) and positive lymph node metastasis (P=0.034)." (PMID 29088849, 2017). "S100A11 targeted to the nucleus and/or cytoplasm activated Smad pathway and induced EMT, which is very similar to tumor-promoting properties of the upstream stimulatory factors LASP1 or TGFβ." (PMID 27181092, 2016). "The newly identified role of LASP1 in regulating matrix degradation by affecting MMP transcription and secretion elucidated the migratory potential of LASP1 overexpressing aggressive tumor cells in earlier studies." (PMID 27588391, 2016). "LASP1, the newly identified regulatory protein in invadopodia in this study, is overexpressed in numerous tumor entities and correlates with tumor aggressiveness." (PMID 27588391, 2016). "IHC staining of metastatic tumor tissues from nude mice revealed that the protein levels of LASP1 in metastatic tumor cells from the Sw620/Lenti-miR-145 group were decreased significantly compared with those from the Sw620/Lenti-NC group." (PMID 27626692, 2016). "It is interesting to note that LASP1 depleted cells with a low cellular LASP1 concentration, exhibit a more profound physiological cytoskeletal network with defined actin stress fibres than the based tumor cell with accumulated intermediate filaments." (PMID 27588391, 2016). "Several of these studies demonstrate that LASP1 expression and nuclear localization are positively correlated with malignancy, tumor grade and metastatic lymph node status." (PMID 26061439, 2015). "Further studies of other tumor entities give evidence for LASP1 mediated cancer aggressiveness as silencing of LASP1 in ECA109 and KYSE510 ESCC cell lines significantly inhibited cell proliferation, migration and invasion in vitro." (PMID 25622104, 2015). "As EMT is an important step in tumor progression and metastasis, these data provide for the first time a possible mechanism of a LASP1-mediated effect on cancer aggressiveness." (PMID 25622104, 2015). "Similar results on tumor suppressive behavior were obtained for another LASP1 targeting miRNA in CRC: miR-1." (PMID 25622104, 2015). "miR-218, as a tumor-suppresser, inhibits cancer cell migration and invasion via the targeting of LASP1 in PCa." (PMID 26622795, 2015). "Several studies demonstrated that LASP1 expression and nuclear localization positively correlated with malignancy, tumor grade, and metastatic lymph node status (for review see:)." (PMID 26061439, 2015). "Tumor-derived cell lines have frequently been used for functional analysis of LASP1 expression in human carcinoma." (PMID 25622104, 2015). "LASP1 is significantly overexpressed in numerous different cancer entities and affects tumor aggressiveness." (PMID 25622104, 2015). "Conversely, ectopic LASP1 overexpression in SW480 CRC cells, which minimally express LASP1 under normal conditions, resulted in an aggressive phenotype with promoted tumor growth and metastasis in a murine xenograft model." (PMID 25622104, 2015). "Since LASP1 has been shown to promote cell motility and metastasis in other tumor entities we analyzed cell migration and adhesion of LNCaP cells before and after LASP1 silencing with a modified Boyden-chamber and an adhesion assay, respectively." (PMID 24980827, 2014).